CXCL1 (C-X-C motif chemokine ligand 1)
Diseases named in the same sentence as CXCL1 in open-access papers (continued):
Sharing a sentence is not in itself a finding about the gene and the disease.
tumor (continued). "In the Guangxi Medical University cohort, we found that the expression of CXCL1 in tumor tissues was significantly correlated with preoperative CEA." (PMID 34405013, 2021). "More research is necessary to investigate if similar mechanisms determine tumour-inhibitory vs. pro-tumour effects of CXCL1 and CCL4." (PMID 34359731, 2021). "CXCL1 modulates the tumor microenvironment (macrophages, fibroblasts, neutrophils, and osteoclasts)." (PMID 33466892, 2021). "IL17RB activates multiple chemokine (such as CCL20/CXCL1/IL8/TFF1) expressions to enhance tumor cell invasion, macrophage, and endothelial cell recruitment at primary sites and cancer cell survival at distant organs." (PMID 34724890, 2021). "In conclusion, miR-145-5p is a tumor suppressor in CC and can inhibit the expression of CXCL1 and ITGA2." (PMID 34860147, 2021). "For certain genes (Il10, Csf3, Cxcl1, Ccl2, Gata3, Il5, and Il13), there was a clear difference between the EC and HC Shb KO effects using Cdh5-CreERt2 or Vav1-Cre tumor-bearing mice, indicating that these effects reflect EC cell autonomy of Shb gene deletion." (PMID 34768912, 2021). "CXCL1, like IL‐6, affects the invasion and migration of tumour cells and induces the recruitment of a variety of cytokines to form a tumour microenvironment that promotes the proliferation of tumour cells." (PMID 34216174, 2021). "Elevated CXCL1 in BC stroma correlates with increased tumor grade, disease recurrence, and poor patient survival and inversely correlates with TGF-β signaling component expression." (PMID 34337083, 2021). "Previous studies indicated that tumor cell-derived CXCL1 promotes the recruitment and infiltration of MDSCs to the tumor site and facilitates HCC metastasis." (PMID 33897880, 2021). "The expression of CXCL1 was markedly up-regulated in tumor tissues, and it decreased as the tumor stage developed." (PMID 34405013, 2021). "This study analyzed the correlation between the expression of CXCL1-2 and tumor purity, T cell CD8+, T cell CD4+, Macrophage infiltration and other immune cells." (PMID 34123826, 2021). "Tumor-derived factors and chemokines, particularly CXCL1, were found to drive neutrophil phenotypical plasticity, inducing NDN to transition towards a low-density state (LD-NDN)." (PMID 34680231, 2021). "The transmigration of neutrophils into the tumour parenchyma can occur by enhanced expression of adhesion molecules and chemokines which include CXCL1, CXCL8 and CCL15." (PMID 33917287, 2021). "CXCL1 and CXCL16 released by PrCa-associated fibroblasts stimulate tumor cell adhesion within the bone matrix." (PMID 34064859, 2021). "miR-200b hasbeen found to inhibit angiogenesis in tumour developmentby targeting interleukin-8 and CXCL1, which are secretedby cancer cells." (PMID 33650820, 2021). "Further evidence of reduced immunosuppression following the combination therapy was a significant decrease in pro‐tumor cytokines, such as IL‐6 and CXCL‐1 in the serum of tumor‐bearing mice (Fig EV4E)." (PMID 33283987, 2021). "In Scotto Cervix 2 Statistics, CXCL1/8/9/10/11/13 were elevated in CC tissues relative to the adjacent tissues of the tumor." (PMID 34321012, 2021). "In conclusion, G9a-mediated silencing of SLC7A2 exerts unexpected functions in cancer metastasis by fostering a tumor-supportive microenvironment through CXCL1 secretion and MDSCs recruitment." (PMID 34108444, 2021). "CSCs also produce various chemokines, such as CCL2 (MCP1), to recruit immunosuppressive CCR2+ cells, including Tregs and MDSCs, and CXCL1/2 to recruit CXCR2+ MDSCs that enhance tumor survival." (PMID 33535613, 2021). "Previous literature has reported that CXCL1 is a critical factor in inflammatory diseases and tumor progression." (PMID 33959656, 2021). "We found that the expression of CXCL1/3/5/6/8/9/10/11/13/16/17 was up-regulated in tumor tissues, while the expression of CXCL12/14 was down-regulated." (PMID 34321012, 2021).
tumor (continued). "The good prognostic effect of infiltrated CXCL1 positive was most likely to indicate the immune function of this chemokine and the anti-tumor effect of inflammatory cells." (PMID 34405013, 2021). "CXCL1, produced in the primary tumor, recruits MDSCs to form the pre-metastatic niche, sustaining homing, survival, and growth of circulating tumor cells in secondary organs leading to metastasis development." (PMID 34195201, 2021). "Our analysis implied that tumor cells co-express CXCL1 and EGFR, but expression levels of CXCR2, HB-EGF, and ADAMs are relatively low." (PMID 33941851, 2021). "We found that tumor-conditioned media and CXCL1 promote LD-NDN formation, suggesting that multiple factors mediate neutrophils’ plasticity." (PMID 34680231, 2021). "Previous findings demonstrated that tumor derived CXCL1 was expressed in stromal cells and epithelial cells, and promoted the cancer growth and its expression level related to the tumor grade." (PMID 34917611, 2021). "Our findings reveal that CXCL1 functions as an autocrine growth factor for BCSCs and elicits primarily tumor progression and immune escape programs." (PMID 34195201, 2021). "Mechanistically, CXCL1 was highly expressed in the tumor clones with low T cell infiltration due to the high levels of H3K4me3 enriched at the promoter region of the Cxcl1 gene." (PMID 33868269, 2021). "In particular, these authors observed that IL1β secreted by cancer-associated macrophages induced the secretion of CXCR2 ligands by CAFs, such as IL8 and GROα (CXCL1), which were ultimately the mediators of such tolerance in tumor cells." (PMID 34066976, 2021). "During in vivo hepatocyte RIS, Cox2 is critical to tumor suppression, Cxcl1 expression, and immune-mediated senescence surveillance, partially through PGE2." (PMID 33730589, 2021). "The quantification of Cxcr2 ligands showed that Cxcl1 and Cxcl5 RNA levels increased in the tumor of PyMT animals compared to wild−type (WT) mammary gland." (PMID 34070438, 2021). "In fact, under conditions of obesity, PCa display increased expression of CXCL1 and IL-8 chemokines, promoting the homing of ASCs to the tumor microenvironment and contributing to tumor growth promotion." (PMID 33922898, 2021). "Depletion of angiogenic factors, including VEGF, CXCL1 and IL-8/CXCL8, prevented tube formation mediated by these NK cells educated by the hypoxic cancer-derived EVs, showing that they all contributed to tumor-associated angiogenesis." (PMID 34944871, 2021). "The RNA sequencing dataset of COAD patients was divided into 2 phenotypes through the median value of CXCL1 expressions in tumor tissues." (PMID 34405013, 2021). "The objective function of CXCL1 in tumor development and the alteration mechanisms and properties after the HDACi treatment still need to be elaborated." (PMID 33959656, 2021). "We further found that deficient SLC7A2 medicated the upregulation of CXCL1 through PI3K/Akt/NF-kκB pathway to recruit myeloid-derived suppressor cells (MDSCs), exerting tumor immunosuppressive effect." (PMID 34108444, 2021). "It accelerates tumor growth by silencing tumor suppressors and DNA repair genes, influences the activity of immune and endothelial cells via CXCL1 and CXCL2 and inactivates ERK, NF-kB and PI3K-AKT pathways resulting in increased levels of β-catenin signaling." (PMID 34944856, 2021). "Among the chemokines regulated by USP12 in tumour cells, CXCL1 and CXCL8 share the chemokine receptor CXCR2 and are strong chemoattractants that recruit TAMs and MDSCs38–40." (PMID 34381028, 2021). "To explore the effect of iCAF induced by CXCL1 on the proliferation of tumor cells, we compared tumor cell proliferation after coculture with CAF stimulated by PBS or rCXCL1 together with or without SB225002." (PMID 34218518, 2021).
tumor (continued). "Tumor‐secreted CXCL1 stimulated the formation of iCAF through CXCR2/pSTAT3, which was blocked by a CXCR2 inhibitor (SB225002)." (PMID 34218518, 2021). "In colorectal cancer, a high level of CXCL1 expression correlates with advanced tumor stage, shorter overall survival (OS) and disease-free survival." (PMID 34195201, 2021). "After 4 weeks, IVIS findings showed that the knockdown of CXCL1 reduced tumor metastasis to the lung." (PMID 34760697, 2021). "CXCL-1 is known to induce Treg cells' chemotaxis into the malignant pleural effusion, allowing the tumours to escape the immune response." (PMID 34336101, 2021). "CXCL1 can promote and enhance the killing of macrophages to tumor cells and microorganisms, regulate the release of cytokines and other inflammatory regulators by macrophages, and stimulate cell phagocytosis." (PMID 34803728, 2021). "A decrease in PMN-MDSC recruitment has been observed after the use of Sema4D mAb to treat murine oral cancer 1 (MOC1); this phenomenon is associated with decreased expression of MAPK-dependent chemokines such as CXCL1, 2, and 5 in tumor cells." (PMID 34403220, 2021). "In bladder cancer patients, urinary CXCL1 can serve as a molecular marker for tumor detection and as a predictor of local recurrence." (PMID 34195201, 2021). "It was found that Cxcl1 overexpression in LLC tumours was sufficient to restore TAM infiltration and PD-L1 expression on TAMs, and led to a significant, albeit not complete, the rescue of CD31-positive cell abundance." (PMID 34381028, 2021). "Analysis of the tumor EV-educated macrophages (TEMs) showed secretion of a variety of factors including CXCL1, CTLA-4, IFNG, OPN, HGF, TGFB, and CCL19 capable of remodeling the surrounding tumor stroma and immune infiltrate." (PMID 34298673, 2021). "After arrest, neutrophils within clusters are highly migratory, in a confined manner mediated by neutrophils self-secreted IL-8 and tumor-derived CXCL-1." (PMID 33101283, 2020). "In tumor therapies, CXCL1 is also responsible for resistance of the cancer cells to several chemotherapeutic drugs." (PMID 32326946, 2020). "Metformin inhibits NF-κB expression by increasing AMPK phosphorylation and inducing Dachshund homologue 1 (DACH1) mRNA expression, thereby reducing MDSCs migration and inhibiting CXCL1 secretion in esophageal carcinoma cells and tumor xenografts." (PMID 33027968, 2020). "Here, we show serum levels of other cytokines in intact (non-tumor induced) mice that, except CXCL1, remained unchanged between young and aged virgin mice, while increased significantly in aged multiparous animals." (PMID 31936467, 2020). "The most differentially and highly expressed cytokine in their cell line experiments was CXCL1, which was also elevated in the serum and muscle of tumor bearing mice." (PMID 33291708, 2020). "We found that tumours of ibrutinib-treated mice expressed significantly lower transcripts of Vegf, Mmp9, and Cxcl1 compared to tumours of the vehicle-treated group." (PMID 32025027, 2020). "This pattern was distinct from the reduced expressions of Ccl2 and Cxcl1 in tumor tissues compared with primary cells." (PMID 32244522, 2020). "Initial studies demonstrated that recombinant as well as tumor cell line-derived CXCL1 induced chemoattraction in vitro and IFN-γ secretion of CXCR2-engineered T cells." (PMID 33680923, 2020). "Neutrophils can have significant anti-tumor activity Expression of CXCL1, CXCL2, and CXCL5 chemokine driven by hypoxia within the tumor microenvironment cause neutrophil recruitment to the tumor site." (PMID 32824655, 2020).
tumor (continued). "The inhibitor AG490 of JAK-STAT signaling pathway was used to identify the functional mechanism of CXCL1/JAK-STAT underlying progression of CRC, and tumor xenograft experiments were performed for further validation." (PMID 34079750, 2020). "Tumor expression levels of Cxcl1 followed a similar trend, suggesting that G-MDSC recruitment persisted even after therapy administration in DIO mice." (PMID 33123173, 2020). "On the other hand, the MDSCs population in tumor tissues was also inhibited by XIAOPI treatment or CXCL1 knockdown in TAMs." (PMID 32213179, 2020). "We further identified EMT and NF‐κB as the downstream signaling pathways of CXCL1 and silencing CXCL1 attenuated tumor progression." (PMID 32187449, 2020). "Next, we analysed the expression of genes such as Vegf, Mmp9, and Cxcl1, which are known to play an important role in tumour progression and metastasis." (PMID 32025027, 2020). "Across cell lines from all tumor types, we observed enrichment of CXCL1 expression in KRASMUT cell lines versus KRASWT cell lines." (PMID 32634121, 2020). "To validate the expression of CXCL1 transcripts from in vivo tumor tissue, we isolated tumors from mice with R248W P72 and R248W R72 (n = 3 for R248W and n = 2 for R248Q, n = 5 total)." (PMID 33126568, 2020). "Previous studies have also demonstrated that CRC cells secrete VEGF-A, which leads to TAMs induction and subsequent production of chemokine (C-X-C motif) ligand 1 (CXCL1) in the primary tumor." (PMID 33384962, 2020). "Increased CXCL1 levels had positive relationships with tumor size, degree of invasion, advancing stage, metastasis, and poor prognosis." (PMID 32351322, 2020). "In the lung with tumor, the RP-G1 patient expressed CXCL-1, ICAM, IL-1ra and MIF while the RP-G3 patient showed those same cytokines but also expressed CD154, IL-23, IFN-γ and PAI-1." (PMID 33109238, 2020). "By secreting IL-8, PMNs were chemotactically confined by tumor derived CXCL-1, which enhanced the extravasation of adjacent melanoma or breast cancer cells through a modulation of the endothelial barrier by IL-8." (PMID 33343560, 2020). "For further verification, 56 pairs of clinical CRC tissue samples and adjacent normal tissue samples were collected for CXCL1 expression detection, finding that the expression of CXCL1 in tumor tissue was significantly higher than that in adjacent tissue." (PMID 34079750, 2020). "Tumor-derived CXCL1 modulates the tumor microenvironment by regulating various cells, such as macrophages, fibroblasts, neutrophils, and osteoclasts." (PMID 32079335, 2020). "Intratumoral protein concentrations of CXCL1 were further found to be elevated in the obese tumor microenvironment." (PMID 33123173, 2020). "UBC cells produce a variety of pro-angiogenic, pro-inflammatory cytokines, such as IL-1, CXCL-1 or IL-6, which accelerate tumour growth and metastasis formation in an auto- and paracrine manner." (PMID 33267794, 2020). "In order to determine the mechanism of neutrophils recruitment into the tumour, we screened neutrophil attracting chemokines (CXCL1, CXCL2, CXCL3, CXCL5, CXCL8 and CXCL12)." (PMID 32778818, 2020). "Recent evidence has demonstrated that tumor-secreted CXCL1 enhances tumor growth via the recruitment of various inflammatory cells or stroma cells into the tumor microenvironment via paracrine or autocrine mechanisms." (PMID 32079335, 2020).
tumor (continued). "Myeloid-derived suppressor cells (MDSC) expressing CXCR2 can be recruited to the developing tumor by CXCL1 and CXCL2, possibly induced by PGE2." (PMID 32276475, 2020). "Others have also demonstrated tumor-derived secretion of CXCL1, which has pleiotropic effects in the tumor microenvironment." (PMID 33291708, 2020). "In the early stages of tumorigenesis, chemokines such as the CXCL1/CXCR2 axis can mediate OIS through NF-κB signalling to restrict tumor growth." (PMID 31991604, 2020). "Tumor xenograft experiments were performed to clarify the role of CXCL1/JAK-STAT in CRC proliferation in vivo." (PMID 34079750, 2020). "During the formation of the tumor metastasis microenvironment, increased secretion of CXCL1 and CXCL2 by endothelial cells and megakaryocytes promotes the release of neutrophils into circulation via the regulation of CXCR2 signaling." (PMID 33363026, 2020). "To further qualitatively visualize the increased CXCL1 expression in mouse tumor tissue, we performed IHC and show that in both mutants R248W and R248Q, the R72 SNP maintains relatively higher levels of CXCL1 expression compared to their P72 counterparts." (PMID 33126568, 2020). "Since HSPCs recruitment and mobilization depended on chemokines secreted by tumor or suppressive immune cells and CXCL1 was validated to promote distant metastasis, we, therefore, detected the effects of CXCL1 on the differentiation of HSPCs." (PMID 32213179, 2020). "CXCL1 expression levels are strongly correlated with the occurrence of certain tumors and promotion of tumor progression through stimulating angiogenesis." (PMID 32256671, 2020). "In the tumor microenvironment of SMAD4-deficient CRC, TANs are recruited via the chemokine CXCL1/8-CXCR2 axis." (PMID 31756952, 2019). "Obese patients with prostate cancer showed increased expression of epithelial CXCL1, which induces the recruitment of adipose stromal cells from white adipose tissue to the tumor and promotes the tumor’s growth." (PMID 30736371, 2019). "Remarkably, only those PSCs located away from tumor cells, denoted as “inflammatory CAFs (iCAFs),” were proficient in secreting pro-stemness factors, including IL-6, CXCL-1, and CXCL-2, through activation of IL-1α-Janus kina (JAK)–STAT signaling." (PMID 31417869, 2019). "Various preclinical studies highlighted the effects of CUR on NF-kB, STAT3, COX2, and CXCL-1 (chemokine [C-X-C motif] ligand 1) activity, leading to reduced inflammation and eventually also impacting tumor progression." (PMID 31013694, 2019). "Ninety percent of PitNETs secreted IL-8, CCL2 and CCL3, while CXCL1 was secreted by 50% of the tumours." (PMID 31703742, 2019). "Cancer cell-derived CXCL1 mediates the recruitment of bone-marrow mesenchymal cells (BM-MCs), one of the origin cells of CAFs, into the tumour microenvironment." (PMID 31147602, 2019). "MCP-1 and CXCL1 (GRO) influence breast carcinogenesis by facilitating tumor growth and metastatic spread." (PMID 30871042, 2019). "IHC staining was performed to evaluate the protein level of DACH1, CXCL1, cyclin D1, and Ki67 in nude mice xenograft tumor tissues from cells expressing vector control and DACH1." (PMID 31998654, 2019). "The increased binds of CXCL1 or CXCL2 to CXCR2 leads to reduced SAP18 expression under tumor conditions, which subsequently activates the ERK/STAT3 signaling pathway to promote mo-MDSCs accumulation." (PMID 31395859, 2019). "CXCL1 is known to enhance tumor stromal interaction leading to enhanced migration and invasion in various cancer." (PMID 30975102, 2019). "The secreted CXCL1 enhanced DNA damage repair of tumor cells by inhibiting ROS-scavenging enzyme superoxide dismutase 1 (SOD1) expression." (PMID 31101063, 2019). "The tumor-suppressive role of STAT3 is attributed to its ability to inhibit NF-κΒ-induced transcription of the proangiogenic chemokine Cxcl1, thereby suppressing tumor vascularization and tumor progression." (PMID 30931929, 2019).